RNU6-1034P (RNA, U6 small nuclear 1034, pseudogene)
Gene: Small nuclear RNA gene on chromosome 17 (29,445,300 to 29,445,400, reverse strand). Ensembl gene ENSG00000202205.
Homologues: Orthologues: chimpanzee U6 (99% identical), macaque U6 (96% identical). Paralogues in human: RNU6-480P (91% identical), RNU6-144P (90% identical), RNU6-16P (90% identical), RNU6-38P (89% identical), RNU6-46P (89% identical), RNU6-87P (89% identical), RNU6-1 (88% identical), RNU6-1179P (88% identical), RNU6-11P (88% identical), RNU6-140P (88% identical), RNU6-2 (88% identical), RNU6-235P (88% identical), and 1288 more.